APC (APC regulator of Wnt signaling pathway)
Diseases named in the same sentence as APC in open-access papers (continued):
Sharing a sentence is not in itself a finding about the gene and the disease.
Familial adenomatous polyposis (continued). "Mutation in the Adenomatous polyposis coli (APC) tumor suppressor gene occurs in over 80% of sporadic colorectal adenomas, and germline mutations in the APC gene result in familial adenomatous polyposis (FAP) syndrome." (PMID 40005135, 2025). "Another study identified APC, a common tumor suppressor gene, and its mutation is associated with familial adenomatous polyposis (FAP) and sporadic colorectal tumors." (PMID 40806235, 2025). "Mutations involving codons 1250–1464 of the APC gene are associated with classical familial adenomatous polyposis." (PMID 39057027, 2024). "APC germline pathogenic variants are associated with familial adenomatous polyposis (FAP), an autosomal dominant colorectal cancer (CRC) predisposition syndrome characterized by the development of hundreds to thousands of colorectal adenomatous polyps." (PMID 39104424, 2024). "Familial adenomatous polyposis (FAP)—FAP is an autosomal dominant condition due to a mutation in APC (adenomatous polyposis coli) gene on chromosome 5q22." (PMID 38893137, 2024). "Familial adenomatous polyposis (FAP) is an autosomal dominant disorder resulting from germline mutations in the APC gene." (PMID 38548799, 2024). "Germ-line APC mutations cause the autosomal dominantly inherited syndrome Familial Adenomatous Polyposis (FAP), with multiple adenomas developing in the gastrointestinal tract." (PMID 39594797, 2024). "FAP is an autosomal dominant inherited disease due to an inactivating mutation in the oncosuppressor gene Adenomatous Polyposis Coli (APC)." (PMID 38794302, 2024). "A minority of DTs are diagnosed in patients with germline APC mutation, which manifests as familial adenomatous polyposis (FAP)." (PMID 38270798, 2024). "Germline mutations in the APC gene result in familial adenomatous polyposis (FAP), an autosomal dominant inherited condition leading to development of multiple intestinal polyps and CRC." (PMID 38590663, 2024). "APC is a tumor-suppressor gene whose mutation has been directly implicated in the development of human familial adenomatous polyposis (FAP) and sporadic CRC." (PMID 39594801, 2024). "Pathogenic constitutional APC variants underlie familial adenomatous polyposis, the most common hereditary gastrointestinal polyposis syndrome." (PMID 39357517, 2024). "Nuclear accumulation seems to be specific to familial adenomatous polyposis-related cribriform–morular thyroid carcinomas (due to the inactivation of both alleles of the APC gene) and to poorly differentiated TCs and ATCs." (PMID 38396644, 2024). "The most common mutation in CRC is APC (adenomatous polyposis coli), which accounts for 85% of total cases, and an inherited APC germline mutation leads to FAP." (PMID 39335155, 2024). "Inherited APC gene pathogenic variants are responsible for familial adenomatous polyposis (FAP) with up to a 100% risk of developing CRC during a person’s lifetime." (PMID 38970018, 2024). "Approximately 5% to 10% arise in the context of familial adenomatous polyposis (FAP) caused by a mutation in the adenomatous polyposis coli (APC) gene." (PMID 38786576, 2024). "Familial adenomatous polyposis (FAP) is an autosomal dominant disorder due to the germline mutation in the APC gene located on chromosome 5q21 and it affects one in 10,000–20,000 people." (PMID 39200847, 2024). "Familial adenomatous polyposis (FAP) is an autosomal dominant syndrome primarily caused by inherited mutations in the APC gene." (PMID 39021676, 2024). "While germline mutation of the APC tumor suppressor gene is the underlying condition for familial adenomatous polyposis (FAP), APC somatic mutations occur in approximately 80% of all CRC cases." (PMID 38424512, 2024). "The most common cause of colorectal adenomatous polyposis is hereditary adenomatous polyposis, typically resulting from germline pathogenic variants in the APC or MUTYH genes." (PMID 38647838, 2024).
Familial adenomatous polyposis (continued). "Germinal mutations in the APC gene are responsible for most cases of familial adenomatous polyposis (FAP)." (PMID 39125905, 2024). "Mutations in the APC gene are responsible for sporadic colorectal tumors and familial adenomatous polyposis." (PMID 39328595, 2024). "Based on etiology, DT is categorized into two main types: sporadic DT (85-90%) and familial adenomatous polyposis (FAP)-associated DT (10-15%) caused by germline mutations in the APC (adenomatous polyposis coli) gene." (PMID 39104718, 2024). "Inactivating APC mutations causes familial adenomatous polyposis (FAP), which is a syndrome characterized by extensive intestinal polyp formation and a high risk of CRC development." (PMID 36766788, 2023). "Conversely, familial adenomatous polyposis (FAP) caused by heterozygous APC germline mutations accounts for only 1% of CRC." (PMID 36831495, 2023). "Intensive studies over the past twenty years have led to the identification of genetic causes of familial polyposis, suggesting that, in addition to the APC gene, other predisposition genes account for a small fraction of the molecular causes of the disease." (PMID 37834005, 2023). "It is well known that APC gene mutations are responsible for familial adenomatous polyposis (FAP), and also play an important role in the initiation and development of colon cancer." (PMID 36977982, 2023). "Pathogenic or likely-pathogenic germline alterations in the APC gene (chromosome 5q22.2) are associated with familial adenomatous polyposis (FAP)." (PMID 36768460, 2023). "FAP has a strong genotype correlation with the susceptibility locus adenomatous polyposis coli (APC), with a germline mutation detection rate of 60–90%." (PMID 36828923, 2023). "Along the same line, and surprisingly, COL11A1 seems to be also overexpressed in colon polyps of patients with adenomatous familial polyposis via mutation in APC." (PMID 37760937, 2023). "While APC gene mutations have been commonly associated with familial adenomatous polyposis and colon cancer, recent studies suggest a role of APC promoter hypermethylation in the malignant evolution of BCa." (PMID 37627010, 2023). "Due to germline mutations in APC (adenomatous polyposis coli), individuals with FAP have literally scores to hundreds of adenomatous polyps." (PMID 37169023, 2023). "Similar low co-occurrences are seen in Familial Adenomatous Polyposis, which is related to the germline mutations of the APC gene." (PMID 36717525, 2023). "Germline adenomatous polyposis coli (APC) mutation in patients with familial adenomatous polyposis (FAP) promotes gastrointestinal polyposis, including the formation of frequent gastric fundic gland polyps (FGPs)." (PMID 37943618, 2023). "Supernumerary teeth have also been reported to be associated with various malformation syndromes, including APC-associated familial adenomatous polyposis (FAP), RUNX2-associated cleidocranial dysplasia, and TRPS1-associated tricho-rhino-phalangeal syndrome." (PMID 36901686, 2023). "About 5–10% of cases occur in patients with familial adenomatous polyposis (FAP), due to an APC (adenomatous polyposis coli) germ line mutation, with the two mutations being mutually exclusive." (PMID 38138880, 2023). "Familial adenomatous polyposis (FAP) is an autosomal dominant disease resulting from an inherited loss-of-function mutation to the tumor suppressor adenomatous polyposis coli (APC)." (PMID 37943618, 2023). "The other main molecular alterations reported are linked to the familial adenomatous polyposis: a somatic APC variant and a 5q deletion, encompassing the APC, in the 5q deletion syndrome." (PMID 38136408, 2023). "Familial kindred specimens were also tested for the E-cadherin mutation and APC (adenomatous polyposis coli)." (PMID 37754493, 2023).
Familial adenomatous polyposis (continued). "Wnt signaling was first reported in human disease when familial adenomatous polyposis was caused by mutations in the adenomatous polyposis coli (APC) gene to some extent and eventually evolved into colon cancers." (PMID 37046749, 2023). "APC, a “gatekeeper” of colonic neoplasia, has been implicated in familial adenomatous polyposis (FAP) syndrome." (PMID 36765950, 2023). "APC’s germline mutations result in familial adenomatous polyposis (FAP), the major hereditary predisposition to CRC development." (PMID 38004598, 2023). "Familial adenomatous polyposis (FAP) is an autosomal dominant disorder caused by germline mutations in the adenomatous polyposis coli (APC) gene." (PMID 38012770, 2023). "The father of patient #4 (high-grade glioma already treated for medulloblastoma, and APC variant) was diagnosed with familial adenomatous polyposis, highly indicative of Turcot’s syndrome." (PMID 38139220, 2023). "Familial adenomatous polyposis syndrome is an autosomal dominant disease, predominantly caused by a germline mutation in the adenomatous polyposis coli (APC) gene on chromosome 5q21." (PMID 36765737, 2023). "Somatic mutations and deletion of APC encoding gene are discovered in most sporadic colorectal adenomas and carcinomas, while germ-line mutations were found in familial adenomatous polyposis." (PMID 35883434, 2022). "Familial adenomatous polyposis (FAP) is an autosomal dominant disorder associated with a germline mutation in the APC gene situated on chromosome 5q21." (PMID 35207172, 2022). "ApcMin/+ mice are heterozygous for a point mutation in the adenomatous polyposis coli (APC) gene, and are widely used to research familial adenomatous polyposis and colorectal tumors." (PMID 36060011, 2022). "Particularly, APC mutations have demonstrated to be related with familial adenomatous polyposis (FAP) which can lead to tumor progression in CRC development." (PMID 35874638, 2022). "Familial adenomatous polyposis (FAP) is an autosomal dominant inherited disease that often results from germline mutations in the adenomatous polyposis coli (APC) gene, a tumor suppressor and polarity regulator." (PMID 35417240, 2022). "APC appears to follow Knudsen’s two-hit theory, as both alleles have been found to be mutated in the majority of adenomas from patients with familial adenomatous polyposis (FAP)." (PMID 35159051, 2022). "Hereditary mutations in APC give rise to familial adenomatous polyposis (FAP), a rare inherited cancer predisposition syndrome in which patients present with hundreds to thousands of precancerous polyps." (PMID 36436127, 2022). "The frequency of APC germline mutations in patients with familial adenomatous polyposis (FAP)-related diseases, such as gastric fundus adenomatous polyposis, duodenal adenoma, desmoid tumors, and thyroid cancer is greater than 60%." (PMID 35991559, 2022). "Individuals with familial adenomatous polyposis (FAP) carry a heterozygous germline mutation in the APC gene and are at increased risk of developing colorectal cancer." (PMID 34980912, 2022). "Heterozygous mutations in APC represent the earliest event in sporadic colorectal carcinogenesis onset and cause familial adenomatous polyposis syndrome." (PMID 34486752, 2022). "Germline mutations in the APC gene cause Familial Adenomatous Polyposis (FAP), an autosomal dominant colon cancer predisposition syndrome affecting as many as 3.2 people per 100,000 individuals." (PMID 35685436, 2022). "Mutations of APC, as seen in familial adenomatous polyposis, block β-catenin degradation and result in hundreds of polyps that progress in CRC at an early age." (PMID 35885529, 2022). "Familial adenomatous polyposis (FAP) is an inherited colorectal cancer (CRC) syndrome resulting from germ line mutations in the adenomatous polyposis coli (APC) gene." (PMID 35999641, 2022).
Familial adenomatous polyposis (continued). "Noteworthy, Gardner's syndrome, a variant of familial adenomatous polyposis, was linked with loss-of-function of germline mutations in the APC gene." (PMID 35397562, 2022). "In an animal model of colorectal tumors and human familial adenomatous polyposis, referred to as APC-deficient mice, Niho and their colleagues found concomitant suppression of hypercholesterolemia and intestinal polyp formation by PPARγ ligands." (PMID 35805464, 2022). "APC is a well-known susceptibility gene for familial adenomatous polyposis (FAP), a hereditary polyposis syndrome with an autosomal dominant pattern of inheritance." (PMID 34476650, 2021). "In the case of familial adenomatous polyposis, an autosomal-dominant syndrome caused by genetic alterations in the adenomatous polyposis coli (APC) gene, patients have the genetic alteration present at the level of the entire colic tract." (PMID 33451052, 2021). "Germline mutation of the adenomatous polyposis coli (APC) gene causes familial adenomatous polyposis, a hereditary tumorous predisposition syndrome, which is diagnosed by detection of adenomatous polyps." (PMID 33947834, 2021). "Familial Adenomatous Polyposis (FAP) is an autosomal dominant disorder in which affected individuals inherit a heterozygous mutation in APC, resulting in an increased predisposition to developing CRC, even at relatively young ages." (PMID 33893330, 2021). "Mutations in APC are known to be causative of familial adenomatous polyposis, colon hepatocellular, and gastric carcinoma together with desmoid tumors." (PMID 33821390, 2021). "Mutations in APC can arise sporadically or originate from a hereditary illness, familial adenomatous polyposis (FAP)." (PMID 33891491, 2021). "Familial adenomatous polyposis (FAP) is associated with germline mutations in the APC tumor suppressor gene and has been implicated in 1% of cases with bowel cancer." (PMID 35154239, 2021). "Researches on APC have usually focused on its loss-of-function variants causing familial adenomatous polyposis." (PMID 33968756, 2021). "APC was found to be the most frequently mutated gene in inherited forms of human cancer, causing multiple polyps in intestines (Familial Adenomatous Polyposis or FAP)." (PMID 34552611, 2021). "A 28-year-old male visited hospital because his mother had been diagnosed with familial adenomatous polyposis (FAP) with a pathological variant of the APC gene." (PMID 34455522, 2021). "In both mouse models and familial adenomatous polyposis patients with heterozygous APC mutations, mutation of the other WT APC allele (“second hit”) is associated with tumorigenesis." (PMID 34000297, 2021). "Familial adenomatous polyposis (FAP) is an autosomal dominant genetic disease caused by mutations in the adenomatous polyposis coli (APC) gene." (PMID 33954154, 2021). "Germline mutations of APC were most frequent and were found in 5 cases (3 nonsense mutations and 2 frameshift deletions), two of which were already diagnosed as familial adenomatous polyposis (FAP)." (PMID 34538872, 2021). "Among them, APC is one the strongest candidate because it is involved in familial adenomatous polyposis, a syndrome that can also cause GC." (PMID 33525650, 2021). "APC germline mutations account for the familial adenomatous polyposis (FAP) hereditary cancer syndrome that is characterized by the development of 100 to 1000 of colorectal adenomatous polyps." (PMID 35127508, 2021). "The lifetime risk of developing CRC is 50–80% for individuals who inherit a germline mutation in the mismatch repair genes (Lynch Syndrome) and 100% for individuals born with a mutation in the APC gene (Familial Adenomatous Polyposis (FAP))." (PMID 33671373, 2021).
Familial adenomatous polyposis (continued). "Familial adenomatous polyposis patients with heterozygous germline APC mutations can develop hundreds of colon tumors that are precancerous." (PMID 34000297, 2021). "In the 46 MSS tumors, a single pathogenic APC mutation, consistent with a diagnosis of familial adenomatous polyposis, as well as another pathogenic mutation in MLH1 were identified." (PMID 34819518, 2021). "APC gene encodes a well-known tumor suppressor gene associated with familial adenomatous polyposis, and the detected variant confirmed the diagnosis of FAP in the patient." (PMID 33807868, 2021). "Sometimes, hereditary CRC are characterized by the loss of APC, a condition originally discovered in the familial adenomatous polyposis (FAP) subjects." (PMID 33672730, 2021). "Loss-of-function APC mutations are pathognomonic for colorectal cancer syndrome familial adenomatous polyposis (FAP) and contribute to the great majority of sporadic colorectal cancer development." (PMID 32961708, 2020). "The genetic mutation of adenomatous polyposis coli (APC) is associated with a higher risk of familial adenomatous polyposis and colorectal cancer." (PMID 32695120, 2020). "Mutations in the adenomatous polyposis coli (APC) gene are the potential cause of familial adenomatous polyposis, known as hereditary colon cancer syndrome." (PMID 33488940, 2020). "APC is one of the other components and germline pathogenic variants in APC are associated with familial adenomatous polyposis." (PMID 32754288, 2020). "In summary, microarray-based NGS and direct sequencing identified a novel mutation, APC: p.W553X, in a large Chinese kindred with familial adenomatous polyposis." (PMID 32194643, 2020). "APC germline mutations give rise to familial adenomatous polyposis (FAP) syndrome (OMIM#: 608456), attenuated FAP, Gardner syndrome (OMIM#: 175100), Turcot syndrome (OMIM#: 276300), and other major hereditary predisposition events leading to CRC development." (PMID 33374459, 2020). "Variant rs459552 (APC) is associated with familial adenomatous polyposis 1 and hereditary cancer-predisposing syndrome." (PMID 32708070, 2020). "Adenomatous polyposis coli (APC) is a tumor suppressor gene; it was cloned from 5q21-22 as a causal gene in familial adenomatous polyposis." (PMID 32121061, 2020). "APC is a tumor suppressor gene which is found to be mutated in the majority of familial adenomatous polyposis (FAP) and sporadic colorectal cancers (CRCs)." (PMID 32265994, 2020). "A female participant had a truncating APC variant (c.1262G>A, p.Trp421*) deemed pathogenic for familial adenomatous polyposis." (PMID 32377377, 2020). "Familial adenomatous polyposis is a hereditary colorectal cancer syndrome that arises from germline mutations in the APC tumor suppressor gene." (PMID 32194643, 2020). "Other than tests for the Mendelian disease genes and a handful of highly-expressed cancer risk genes such as BRCA1, BRCA2, and APC (adenomatous polyposis coli), few single-gene tests have demonstrated clinical utility." (PMID 32342786, 2020). "Mutations in adenomatous polyposis coli (APC) gene in familial adenomatous polyposis, Adenine DNA mutY gene in Peutz–Jeghers syndrome and chronic inflammatory bowel disease are also identified causes of CRC." (PMID 32435475, 2020). "Missense pathogenic variants are rare in some genes, including APC, the gene responsible for Familial Adenomatous Polyposis (FAP)." (PMID 32750050, 2020). "A small proportion of CIN tumors are inherited and arise secondary to germline mutations in the APC gene as seen in familial adenomatous polyposis (FAP) or the MUTYH gene (as seen in MUTYH-associated polyposis)." (PMID 32231042, 2020). "The APC gene was initially identified as being causative for the familial adenomatous polyposis (FAP) syndrome." (PMID 31758407, 2020). "CMV-PTC is highly associated with heterozygous germline APC mutations leading to familial adenomatous polyposis (FAP)." (PMID 31598872, 2020).